ALB (albumin)
Diseases named in the same sentence as ALB in open-access papers (continued):
Sharing a sentence is not in itself a finding about the gene and the disease.
Hypoalbuminemia (continued). "In the context of infection, capillary permeability increases, causing albumin to seep from the plasma into the interstitial space, resulting in hypoalbuminemia." (PMID 38912203, 2024). "The patient’s nutritional status was closely monitored, with regular assessments of serum albumin levels and overall nutritional intake, ensuring that the dietary intervention was effectively addressing hypoalbuminemia and other nutritional deficiencies." (PMID 39233993, 2024). "This is particularly interesting because low serum albumin (hypoalbuminemia) is recognized as a risk factor for all-cause, cancer, cardiovascular, and respiratory mortalities." (PMID 39337475, 2024). "Hypoalbuminemia was independently associated with mortality when compared to serum albumin >40 g/L (Hazard Ratio (HR) = 1.61, 95% Confidence Interval: 1.21–2.13)." (PMID 39010980, 2024). "Except for low albumin closely associated with inflammation, hypoalbuminemia predicted the risk of AKI in in-hospital patients and non-cardiac surgery." (PMID 38957440, 2024). "The association between albumin levels and the risk of cardiovascular events was independent of advanced age, sex, multimorbidity, and other causes of hypoalbuminemia." (PMID 38323429, 2024). "Albumin regulates plasma oncotic pressure and transports physiological metabolites and lower levels of blood albumin (hypoalbuminemia) have been associated with poor nutrition or inflammation." (PMID 39666115, 2024). "Compared to normal albumin, hypoalbuminemia was significantly associated with the female gender (P = 0.047), older age groups (P = 0.041), dependent functional status (P < 0.001), and ASA classification ≥ 3 (P = 0.005)." (PMID 38972926, 2024). "Albumin injections have emerged as a potential alternative treatment for edema due to liver disease, addressing hypoalbuminemia symptoms caused by liver failure." (PMID 39099956, 2024). "Excessive albumin losses during HC (haemocatharsis) are considered a potential cause of hypoalbuminemia—a key risk factor for mortality." (PMID 38238597, 2024). "Hypoalbuminemia, as defined by serum albumin (SA) levels ≤35 g/L, is associated to venous and arterial thrombosis in general population and in patients at risk of cardiovascular disease." (PMID 39165413, 2024). "During the acute inflammatory phase, serum albumin levels are inversely correlated with systemic inflammation, which is supported by findings that hypoalbuminemia is associated with elevated inflammatory markers." (PMID 39574520, 2024). "Compared to normal albumin status, hypoalbuminemia was independently associated with a significantly greater likelihood of experiencing any complications, sepsis, blood transfusions, non-home discharge, readmission, and LOS > 2 days." (PMID 38972926, 2024). "A dose-dependent relationship between admission hypoalbuminemia and 30-day readmission was observed, with a higher incidence of 30-day readmission associated with decreasing admission albumin levels." (PMID 38528491, 2024). "The results showed that albumin infusion significantly reduced the incidence of hypotension, indicating that hypoalbuminemia is a modifiable risk factor that can be quickly corrected with albumin supplementation." (PMID 39723253, 2024). "Patients with hypoalbuminemia (serum albumin < 35 g/L) on admission had a significantly higher risk of 30-day readmission compared to those with normal albumin levels (≥ 35 g/L) (OR 2.666, 95% CI 1.902–3.738, p < 0.001)." (PMID 38528491, 2024). "Hypoalbuminemia significantly elevates the risk of death, with a 7.228-fold increase compared to normal albumin levels (OR 7.228, p < 0.001, CI 2.391-21.852)." (PMID 39493167, 2024). "The ALB gene encodes albumin, which possesses anti-inflammatory, antioxidant, anticoagulant, and antiplatelet aggregation activities, so hypoalbuminemia is an independent prognosticator of many cardiovascular diseases, including ischemic heart disease." (PMID 39281275, 2024).
Hypoalbuminemia (continued). "Based on this, the aim of the study was to assess if in general population a relationship between hypoalbuminemia, as defined by serum albumin ≤35 g/L, mortality, and cause-specific mortality does exist." (PMID 39010980, 2024). "The association between TD and hypoalbuminemia in PLN is frequently suggested to be because of the correlation between renal losses of albumin and antithrombin, with deficiency of the latter leading to hypercoagulability." (PMID 38147488, 2024). "Studies have linked hypoalbuminemia (albumin < 35 g/L) to increased postoperative complications and mortality rates in epithelial ovarian cancer." (PMID 39050577, 2024). "Another factor involved in the risk of developing infections is hypoalbuminemia, as albumin binds to pro-inflammatory cytokines and immunosuppression mediators." (PMID 39337069, 2024). "In this retrospective study of the role of serum albumin in 325 HDMTX 5g/m2 courses given to children with ALL we found that hypoalbuminemia was a frequent occurrence, apparently caused by preceding asparaginase therapy." (PMID 39305296, 2024). "Hypoalbuminemia, which is related to weakened antioxidant and antithrombotic capacities of albumin, mainly raises cardiovascular risk." (PMID 39339776, 2024). "The leakage of lymphatic fluid into the gut lumen leads to a significant loss of plasma proteins, particularly albumin, immunoglobulins, and lymphocytes, resulting in hypoproteinemia, hypoalbuminemia, and lymphopenia." (PMID 39233993, 2024). "In our study, in multivariate analysis, the predictive factors associated with higher risk of HT were hypoalbuminemia (serum albumin < 3.5 g/dL) and organ-damage compression by lymphoma." (PMID 39682103, 2024). "Albumin plays a pivotal role in both wound healing and immune function, thereby suggesting that the association between preoperative hypoalbuminemia and puerperal infection is likely to be multifaceted." (PMID 39723193, 2024). "Hypoalbuminemia is likely to increase the free fraction of warfarin and increase the risk of bleeding, because warfarin is mainly bound to serum albumin." (PMID 38440292, 2024). "Although the choice of liquids, particularly colloidal solutions, remains contentious, guidelines advocate for albumin supplementation in cases of hypoalbuminemia resulting from extensive ascites and blood loss." (PMID 39664174, 2024). "Secondly, hypoalbuminemia (low serum albumin levels) is associated with an increased risk and severity of infectious diseases." (PMID 39039519, 2024). "Conversely, we observed a higher prevalence of hypoalbuminemia in individuals aged 65 years or older reinforcing previous reports showing an inverse association between serum albumin and elderly population." (PMID 39010980, 2024). "Our research indicated a connection between hypoalbuminemia at the time of admission and a rise in the likelihood of urinary tract infections, exhibiting a dose-response relationship where lower albumin levels corresponded with a heightened risk of infection." (PMID 39076765, 2024). "Decreased serum albumin levels 6 h after surgery significantly impacted the left-side pleural effusion development, and moderate hypoalbuminemia raised the risk of left-sided pleural effusions by three times after surgery." (PMID 39336439, 2024). "COPD is a chronic inflammatory disease and albumin is susceptible to oxidation under conditions of oxidative stress and chronic inflammation, leading to marked hypoalbuminaemia." (PMID 39643902, 2024). "The top feature across both scoring metrics was associated with hypoalbuminemia (low albumin levels <3 g/dL), which has been shown to correlate with inflammation, shock, and sepsis." (PMID 38179280, 2023). "Approximately 95% of serum DHEA-S is bound to albumin; therefore, hypoalbuminemia or elevated urinary albumin excretion is associated with low serum DHEA-S levels." (PMID 37745694, 2023).
Hypoalbuminemia (continued). "Hypoalbuminemia, diagnosed at albumin levels <35 mg/mL, has recently been significantly associated with increased risk and adverse outcomes of deep musculoskeletal S. aureus infections." (PMID 38014966, 2023). "Further analysis of kidney function parameters on admission revealed a significant association of hypoalbuminemia (serum albumin < 3.5 g/dL) with proteinuria (p = 0.040)." (PMID 37767096, 2023). "Cox proportional risk model was performed to assess the risk of all-cause mortality associated with albumin levels and hypoalbuminemia combined with CMDs." (PMID 37957767, 2023). "A positive association between serum albumin and animal protein intake has been reported, and hypoalbuminemia has been reported to be a risk factor for all-cause mortality and CVD." (PMID 37558986, 2023). "The administration of albumin reduces this risk, and in cases of hypoalbuminemia, the administration of albumin should be considered as an adjunct treatment to phototherapy, regardless of the primary cause of NHB." (PMID 37892362, 2023). "The loss of albumin and resultant hypoalbuminemia results in increased hepatic synthesis of fibrinogen and other procoagulant factors." (PMID 37680313, 2023). "Hypoalbuminemia (generally due to albumin loss in the urine or intestinal tract and to decreased hepatic albumin synthesis) contributes to a decrease in oncotic pressure, also resulting in edema formation." (PMID 37692998, 2023). "It is known that hypoalbuminemia can lead to pleural effusion, so when doctors notice effusions in patients with low albumin levels, they should investigate other possible causes with thorough clinical evaluations." (PMID 37241051, 2023). "In the celiac groups, children showed hypoalbuminemia with the lowest level (2.7 g/dl) in group D. Albumin deficiencies among celiac patients have been described by many authors." (PMID 36778054, 2023). "In dialysis patients, the causes of hypoalbuminemia are multifactorial—a result of imbalance between albumin loss into dialysate, catabolism, and albumin synthesis." (PMID 37892773, 2023). "HSA oxidation is associated with reducing HSA plasma levels and hypoalbuminemia, and high levels of oxidized protein forms are associated with predicting severe COVID-19 and a higher mortality risk." (PMID 36982882, 2023). "Lower levels of albumin were associated with increased risks of all-cause death in a cohort of centenarians, and this risk was enhanced when hypoalbuminemia combined with multiple CMDs." (PMID 37957767, 2023). "In this phase Ib trial, ficlatuzumab, gemcitabine, and albumin-bound paclitaxel were associated with durable treatment responses and increased rates of hypoalbuminemia and edema." (PMID 36807743, 2023). "Since hypoalbuminemia is one of the strongest risk factors for mortality in dialysis patients, peritoneal protein and albumin loss was investigated thoroughly as a cause of hypoalbuminemia and a contributing factor to the patients’ morbidity and mortality." (PMID 37048753, 2023). "Oxidative stress and the albumin oxidized form can lead to hypoalbuminemia, which is a predisposing factor for reduced treatment effectiveness and an increased mortality rate in severe COVID-19 patients." (PMID 36982882, 2023). "Albumin is an essential protein for nutrition transport and body metabolism, and hypoalbuminaemia is associated with poor outcomes in various tumours." (PMID 38031022, 2023). "The presence of baseline azotemia, hypoalbuminemia, and magnitude of baseline creatinine, albumin, and UPC were all negatively associated with 12‐month survival." (PMID 37815154, 2023). "Hypoalbuminemia, which can result from albumin loss in ascitic fluid and low levels due to acute-phase reactions in decompensated liver disease and ascitic fluid infection, has been recognized as an independent risk factor for venous thromboembolism." (PMID 38186444, 2023).
Hypoalbuminemia (continued). "The common association between these studies is that hypoalbuminemia, defined as albumin concentrations <34 g/L, along with a CD4+ T cell count below 500 cells/mm3, are associated with more rapid progression of AIDS." (PMID 37736888, 2023). "During sepsis, the inflammatory response induced by infection influences the synthesis and degradation of albumin, resulting in reduced levels of albumin in the plasma and causing hypoalbuminemia." (PMID 37817258, 2023). "We found a reduction in serum albumin levels after surgery in both groups; however, patients under UM associated with OH had hypoalbuminemia throughout the postoperative period." (PMID 36899784, 2023). "The hypoalbuminemia is a disorder caused due to the low albumin production, which can be related to chronic wound complication, wherein the albumin infusion and protein administration are some of the treatments practiced in the wound of hypoalbulminemia." (PMID 37242594, 2023). "Low levels of albumin are also a surrogate marker of nutritional status, and hypoalbuminemia represents a risk factor for perioperative complications." (PMID 37762867, 2023). "After PSM, a dose > 100 g within a week after admission for hypoalbuminemia patients with albumin infusions was associated with lower mortality than a dose ≤ 100 g (OR:0.51, 95%CI:0.28–0.90, P = 0.020)." (PMID 37277756, 2023). "In subgroup analyses, doses > 100 g within 1 week after admission for hypoalbuminemia patients with albumin infusions was associated with lower mortality than doses ≤ 100 g (OR: 0.51, 95% CI: 0.28–0.90, P = 0.020)." (PMID 37277756, 2023). "A previous study evaluating hypoalbuminemia, mortality, and morbidity in patients undergoing left ventricular device implantation stated that serum albumin < 2.5 g/dL is a risk factor for mortality and morbidity." (PMID 37082727, 2023). "Specifically, albumin preparations should be administered when hypoalbuminemia occurs because of bleeding, increased capillary permeability, decreased albumin synthesis in the liver, excess loss from the kidneys and intestines, and accelerated metabolism." (PMID 37316550, 2023). "Hypoalbuminemia raises cardiovascular risk mainly related to weakened antioxidant, oncotic pressure-maintaining, and antithrombotic capacities of albumin." (PMID 36966329, 2023). "Although the clinical efficacy of ALB supplementation is still debated, it is conceivable to consider the treatment of all possible underlying conditions leading to hypoalbuminemia as a huge priority in the management of CV diseases." (PMID 37762957, 2023). "Acute and chronic inflammation can cause hypoalbuminemia through protein metabolism through inflammatory mechanisms, reducing albumin synthesis and inducing increased capillary permeability." (PMID 37055773, 2023). "ACLD patients display a reduction in protein synthesis such as albumin and coagulation factors causing hypoalbuminemia and aggravating the free water accumulation, and coagulation disorders." (PMID 36676081, 2023). "Disease severity, often linked to hypoalbuminemia, influences albumin dose requirements in the liver." (PMID 38139434, 2023). "Serum albumin is considered a clinical monitoring tool for nutritional assessment, and hypoalbuminemia has been shown to be strongly associated with complications and mortality in the elderly." (PMID 37127636, 2023). "Causes of hypoalbuminemia in the dogs included intestinal loss of albumin, renal loss, loss through increased vascular permeability, reduced synthesis, reduced intake, and other causes and were different between the study groups (p = 0.013)." (PMID 37342623, 2023). "At the moment of diagnostic 21 out of 29 (72.4%) had low levels of albumin (<3.5 g/dL), including three patients (10.3%) with clinically significant hypoalbuminemia (<2.5 g/dL)." (PMID 37275492, 2023).
Hypoalbuminemia (continued). "Several protective effects of serum albumin have been proposed to explain the persistent association of hypoalbuminemia and worse clinical outcomes after controlling for major clinical covariates." (PMID 36362771, 2022). "Chemokines increase vascular permeability and cause the extravascular spillage of albumin, which causes hypoalbuminemia." (PMID 36004962, 2022). "Hypoalbuminemia is associated with inflammation due to increased capillary permeability that favors transcapillary leakage of serum albumin." (PMID 36278562, 2022). "The fact that in the nephrotic condition albumin is cleared as a 36 Å molecule is supported by the finding that the loss of plasma albumin to give rise to hypoalbuminemia is quantitatively accounted for by the appearance of albumin in the urine." (PMID 36225307, 2022). "Preoperative albumin greater than or equal to 40 g/L is a protective factor for postoperative hypoalbuminemia, for patients with preoperative albumin ≥40 g/L, their postoperative protein loss is more than that of patients with preoperative albumin <40 g/L." (PMID 35571899, 2022). "Serum albumin is influenced by inflammation, and numerous studies have shown a strong association between hypoalbuminemia and mortality." (PMID 36644346, 2022). "The objective of our study was to pertinently define the recommended preoperative serum albumin value based on the risk factors of postoperative hypoalbuminemia in patients with STB." (PMID 35571899, 2022). "Fewer complications of hypoalbuminemia, gastrointestinal complications such as weight loss, and infections were noted as well as fewer blood and albumin infusions needed in the intervention group." (PMID 36550508, 2022). "Volume overloading can lead to underestimation of the actual serum albumin level, and hypoalbuminemia can be associated with increased extracellular water via decreased osmotic pressure." (PMID 35299757, 2022). "Hypoalbuminemia is a disorder caused by low albumin production rates or an increased loss due to several possible reasons." (PMID 35160450, 2022). "The reduction in serum total protein content is due to hypoalbuminemia caused by decreased albumin synthesis, which is the direct or indirect effect of the parasite on hepatocytes, leading to liver failure." (PMID 36590791, 2022). "Hypoalbuminemia was associated with operation time (OR 1.011, P < 0.001), preoperative albumin (OR 0.864, P = 0.015) and peroperative globulin (OR 1.192, P = 0.004)." (PMID 34996896, 2022). "These many different functions of albumin explain the association of hypoalbuminemia with poor prognosis in patients with malignancies." (PMID 36316884, 2022). "Hypoalbuminemia is also one of significant characteristics in these patients, which likely to have been caused by an imbalance between ALB synthesis and catabolic rate, and secondary to an active inflammation." (PMID 36225581, 2022). "Complicated with pulmonary tuberculosis, low preoperative albumin value and long operation time are three main independent risk factors that can result in postoperative hypoalbuminemia in patients with thoracic and lumbar tuberculosis." (PMID 35571899, 2022). "Elderly age (OR, 2.594; 95% CI, 1.081–6.185), lower body mass index (BMI, OR, 6.801; 95% CI, 1.575–7.055), and lower albumin (OR, 9.348; 95% CI, 3.601–8.392) were higher risk factors of developed hypoalbuminemia." (PMID 35330404, 2022). "Combined with the diagnostic threshold of hypoalbuminemia, we proposed the preoperative albumin safe values of the patients with thoracic and lumbar tuberculosis." (PMID 35571899, 2022). "While studies have demonstrated an association between preoperative hypoalbuminemia and adverse clinical outcomes, the optimal serum albumin threshold for risk-stratification in the broader surgical population remains poorly defined." (PMID 36362771, 2022). "We primarily focused on albumin, as hypoalbuminemia is often diagnosed in cancer and associated with poor outcome." (PMID 35804981, 2022).